IL10 (interleukin 10)
Diseases named in the same sentence as IL10 in open-access papers (continued):
Sharing a sentence is not in itself a finding about the gene and the disease.
colitis (continued). "UC and experimental intestinal inflammation models including DSS, trinitrobenzene sulfonic acid-induced colitis, and IL-10 knockout mice are characterized by NF-κB activation and increased expression of proinflammatory NF-κB target genes." (PMID 39850943, 2025). "We demonstrate that the STING/RELA axis is required for IL-10 production in monocytes with LGG treatment in colitis." (PMID 39895628, 2025). "To study the relationship between the circadian clock, intestinal inflammation, and colitis, we used the IL-10-/- mouse model for experimental colitis and altered light–dark cycles to disrupt circadian rhythmicity (E.1)." (PMID 39843997, 2025). "In IL-10-/-mice with spontaneous colitis, miR-142-3p and miR-142-5p were significantly increased in colonic mucosa." (PMID 40869073, 2025). "The study found that CW notably reduced the mRNA levels of pro‐inflammatory markers including TNF‐α, IL‐1β, IL‐6, Toll‐like receptor 4 (TLR4), and iNOS, while it enhanced the expression of the anti‐inflammatory cytokine IL‐10 in colitis." (PMID 39830908, 2025). "The treatment of the wild-type DSS-induced colitis group improved the inflammatory response by increasing gut–homeostatic cytokines, such as interleukin-10 (IL-10) and tumor necrosis factor-alpha (TNF-α)." (PMID 40872478, 2025). "Concurrently, AmTARS promotes the restoration of IL-10-positive macrophages, elevates serum IL-10 levels, and mitigates inflammation in colitis mice." (PMID 40028328, 2025). "Collectively, these findings indicate that STING, TBK1, and RELA are critical components of IL-10 activation by LGG in the context of colitis." (PMID 39895628, 2025). "The histology of colitis in these mice was similar to that of human IBD, making the IL10-deficient mice a valuable experimental IBD model." (PMID 40649879, 2025). "Oral administration of live LGG effectively alleviated dextran sodium sulfate–induced (DSS-induced) intestinal inflammation colitis through IL-10 upregulation in intestinal Ly6C+ monocytes." (PMID 39895628, 2025). "When we analyzed the expression of anti‐inflammatory cytokine IL‐10, I3C increased its mRNA levels both in WT colitis mice and AhR∆IEC colitis mice thereby suggesting that the ability of I3C to induce IL‐10 was independent of AhR expression on CECs." (PMID 40410944, 2025). "In colitis mice, resveratrol treatment increased the number of Treg cells as well as IL‐10 and downregulated the number of Th17 cells in the MLN." (PMID 40488195, 2025). "Indolepropionic acid alleviates DSS-induced colitis in mice, reducing tissue abundance of Th1 cells, increasing the population of regulatory T cells, and enhancing IL-10 production." (PMID 40292216, 2025). "TNF-α, IL-1b, and IL-6 have been shown to promote colonic inflammation, with TNF-α causing damage to the intestinal mechanical barrier, and IL-10 and IL-12, which are anti-inflammatory cytokines, which can inhibit inflammation." (PMID 39723143, 2024). "Unlike macrophage, specific deletion of IL-10 in CD4+ T cells (∼80% are Tregs) leads to the development of spontaneous colitis in mice, similar to the phenotype of complete IL10−/− mice." (PMID 38502145, 2024). "In the present study, the behavior of TNF-α and IL-10 in the blood of a mouse model of DSS-induced colitis was similar to that previously reported." (PMID 38542428, 2024). "NFIL3 is IL-10 inducible and serves a primary function as a IL-12p40 transcriptional repressor that suppresses inflammation in colitis." (PMID 39015676, 2024). "An 11-member microbiota consortium GUT-108 reversed colitis in Il10−/− mice by increasing LCA and DCA, decreasing colitogenic Enterobacteriaceae, and increasing beneficial resident Clostridium (Clusters IV and XIVa) species, including Lachnospiraceae." (PMID 39767816, 2024). "The DNBS- or TNBS-induced colitis, which emulates environmental inflammatory bowel disease induction, is alleviated by prior T. spiralis or H. polygyrus infection in an IL-10-dependent manner." (PMID 38277692, 2024).
colitis (continued). "SHIP1 agonist, with an anti-inflammatory “IL-10 mimetic,” effectively inhibited macrophage activation and resolved colitis in IL-10 receptor knock-out mice." (PMID 38251210, 2024). "Oral administration of low concentrations of the emulsifiers carboxymethylcellulose (CMC) and polysorbate-80 (P80) induced severe colitis in IL-10 knockout mice, but only mild inflammation in wild-type mice." (PMID 39249550, 2024). "Conversely, specific deletion of CD1d in IECs, results in reduced IL-10 production and severe oxazolone-mediated colitis." (PMID 38579449, 2024). "infection triggers spontaneous colitis in mice with suppressed IL-10 signaling or in immunodeficient mice." (PMID 39379604, 2024). "For instance, previous studies have shown that Clostridium butyrate can induce the production of Il10 in the intestine, thereby alleviating experimental colitis in mice." (PMID 39560359, 2024). "LP-HFY11 lowered the interleukin-10 (IL-10) level and increased the IL-2 level in the serum of colitis mice." (PMID 38790796, 2024). "In our previous study, we found that CD4+ Treg-of-B cells can alleviate the intestinal inflammation and suppress Th1 and Th17 cytokines IFN-γ, TNF-α, and IL-17 in CD4+CD45RBhi T cell-induced colitis through an IL-10-independent mechanism." (PMID 39085655, 2024). "It’s worth emphasizing that Sema7a, a hub mRNA, plays a part in anti-colitis effects by stimulating macrophage IL-10 production." (PMID 38308210, 2024). "Its colonization can augment Foxp3/RORγt regulatory T cells (Treg cells) and induce IL-10 production, thereby mitigating colitis in mice." (PMID 39408951, 2024). "Pooled human IBD patient fecal microbiota engrafted germ-free (GF) mice with low amplicon sequence variant (ASV)-level transfer efficiency, resulting in high recipient-to-recipient variation of microbiota composition and colitis severity in HMA Il-10−/− mice." (PMID 39113097, 2024). "Il10−/− mice, a classic animal model of spontaneous colitis and mesenteritis, mimics human CD and displays overt lymphatic vessel dysfunction and mesenteric hypertrophy." (PMID 39623906, 2024). "In this model, IL-10 signaling in CX3CR1+ macrophages is crucial for preventing spontaneous colitis." (PMID 39379604, 2024). "Il10–/– mice demonstrated the spontaneous colitis phenotype as evidenced by decreased activity, diarrhea, excreted perianal mucus, dehydration, and diminished weight gain at 7 weeks of age." (PMID 39576011, 2024). "T cell-derived IL-10 dominantly controls intestinal responses with T cell-specific IL-10 mutant mice developing colitis to a similar level as Il10−/− mice." (PMID 38609547, 2024). "Germ-free conditions ameliorate inflammation in various colitis models (e.g., IL10−/− mice), and fecal microbiota transplantation from dysbiotic T-bet−/−RAG2−/− UC mice induces colitis in wild-type mice." (PMID 39293401, 2024). "Wounding of mouse skin was shown to result in the acquisition of increased sensitivity to colitis following oral challenge with dextran sodium sulfate (DSS), or in an experimental model of spontaneous colitis in IL10−/− mice." (PMID 38589392, 2024). "Oral ingestion of PM10 altered the microbiome and generated inflammatory responses in IL-10−/− mice—a genetic model of spontaneous colitis—7 and 14 days after gavage." (PMID 39000289, 2024). "It is noteworthy that Sema7a has been recognized for its role in stimulating colon macrophages to produce IL-10, aligning with previous research which attributes anti-colitis effects to Sema7A." (PMID 38308210, 2024). "Macrophages isolated from the intestinal mucosa of TNBS-induced colitis mice showed increased mRNA levels of iNOS and IL-12p40 (M1 polarization markers) and decreased mRNA levels of IL-10 and Arg-1 (M2 polarization markers) compared with control mice." (PMID 38796413, 2024). "IP MSC treatment in a colitis model has been shown to polarise macrophages to induce IL-10+ T and B cells." (PMID 39551813, 2024).
colitis (continued). "Of note, on the genus level, we found several taxa that significantly differed in abundance between the groups in the transfer colitis model, but only one taxon in the Il10−/− model." (PMID 38839272, 2024). "It is established that TNF‐α, IL‐6, and IL‐1β are key proinflammatory cytokines involved in the onset of colitis, and IL‐10, an anti‐inflammatory cytokine, increases following Res administration in IBD patients." (PMID 38372468, 2024). "Early studies noted upregulated CD1d expression in splenic IL-10+ B cell subsets in murine models, which correlated with colitis." (PMID 39346706, 2024). "CD8+ Tregs from IL-10 knockout mice lose their ability to suppress colitis, indicating that IL-10-secreting CD8+ Tregs play a crucial role in the prevention of IBD." (PMID 39085655, 2024). "In Cluster 1, colitis γδT cells from the colon, epithelial cells, and IL-10 STIM macrophage were activated." (PMID 39513039, 2024). "In our study, we observed a negative correlation between the abundance of Bacteroidaceae and Bacteroides and the levels of TJ proteins and IL-10, while a positive correlation was noted with inflammatory markers of colitis." (PMID 39458282, 2024). "Next, Interleukin 10 knock‐out (Il‐10−/−) mice were used to assess the biological functions of CrF‐EVs in spontaneous mesenteritis and colitis." (PMID 39623906, 2024). "When cotransferring naive T cells from IL-27rα−/− mice with B cells from WT mice into B6 DKO mice, there was severe colitis, and IFNγ and IL-17A expression in colonic tissue explants was increased and IL-10 expression was reduced." (PMID 38566992, 2024). "eTreg cells and IL-10 are more enriched in LP at homeostasis, in contrast to colitis, suggesting that there are likely to be unique interactions that are lost in the context of inflammation, where dendritic cells dominate the LP." (PMID 38570678, 2024). "The intragastric administration of Lactobacillus lactis secreting interleukin-10 (IL-10) led to a substantial 50% reduction in colitis among DSS-treated mice and effectively prevented the onset of colitis in IL-10−/− mice." (PMID 38739270, 2024). "Collectively, our findings show that Blimp-1 and c-Maf cooperate to positively regulate Il10 expression and to directly control genes encompassing the type 1 effector cell responses to prevent severe H. hepaticus-induced colitis." (PMID 38609547, 2024). "Exosomes derived from IL-10-treated bone marrow-derived DCs reduced the severity of drug-induced colitis in mice." (PMID 38255819, 2024). "ELISA results indicated that DSS-induced colitis mice administered with PSPRS showed higher IL-10 and IgA levels but lower TNF-α, IL-1β, and IL-6 levels." (PMID 38611336, 2024). "CrF‐EVs significantly attenuated spontaneous mesenteritis and colitis in Il‐10−/− mice via promoting lymphangiogenesis and lymphatic drainage." (PMID 39623906, 2024). "Subsequently, neutralizing anti-IL10 autoantibodies were identified in an older child with milder colitis, suggesting a potential spectrum of disease and/or a disease-modifying effect." (PMID 39083772, 2024). "Lactobacillus limousine FPHC2951 has been observed to increase the expression of interleukin-10 (IL-10) mRNA, thereby improving symptoms of colitis." (PMID 39835278, 2024). "Here, fecal let-7b and miR-21 were found elevated, associated with inflammation, and correlating with multiple bacteria in IBD patients and IL-10–/– mice, model of spontaneous colitis." (PMID 39224018, 2024). "It has also been reported that compounds that modulate the metabolism of Trp by the gut microbiota induced IL-10 and suppressed inflammation in a mouse colitis model." (PMID 38542428, 2024). "IL-10, a significant anti-inflammatory cytokine, decreases mouse colitis through inhibiting the production of pro-inflammatory cytokine and suppressing the inflammation in the intestines." (PMID 38254526, 2024).
colitis (continued). "In IL-10-deficient mice, Glyburide suppressed NLRP3 inflammasome activation, acting both preventively and by improving ongoing colitis." (PMID 39684769, 2024). "For example, a Lactococcus lactis strain was engineered to express and secrete the anti-inflammatory cytokine IL-10 to treat colitis." (PMID 38276061, 2024). "Quercetin-loaded microcapsules decreased macroscopic edema and neutrophil activation, attenuated histological involvement, and increased IL-10 production in an acetic acid-induced colitis model in mice." (PMID 39451206, 2024). "Some microbiome-based therapies such as fecal microbial transplantation and probiotics have been indicated to modulate IL-10 immune pathways and inhibit experimental colitis." (PMID 38612971, 2024). "Pretreatment with CpG-oligonucleotides in a DSS-induced colitis mouse model results in increased anti-inflammatory cytokine (IL-10) and decreased pro-inflammatory cytokine (IFN-γ) levels, supporting the immune modulatory effect of CpG motifs." (PMID 38019021, 2024). "In several previous studies, it was determined that while spontaneous colitis occurred in IL10−/− mice, the levels of IL-6 were also increased." (PMID 39105785, 2024). "In contrast, mouse-to-mouse transfer of mouse-adapted human IBD patient microbiota transferred with high efficiency and low compositional variability resulting in highly consistent and reproducible colitis phenotypes in recipient Il-10−/− mice." (PMID 39113097, 2024). "In the TNBS-induced colitis group, the anti-inflammatory cytokine IL-10 levels in colonic tissue were significantly suppressed (p < 0.01 or p < 0.001), suggesting that both AL0035 and mesalazine treatments revealed to slow down this process." (PMID 38612971, 2024). "Short-term treatment with anti-miR-21 showed comparable anti-inflammatory effects on the acute colitis as those previously observed in IL-10–/– mice." (PMID 39224018, 2024). "Our results indicated that mice in the colitis-induced Group II showed a significant decrease (p < 0.005) in IL-10 levels (28.66 ± 0.46) compared with the normal Group I (45.46 ± 0.98)." (PMID 39444692, 2024). "It was observed that OA inhibited DSS-induced colitis in Th17 cells by suppressing the expression of IL-1, NF-ĸB, MAPK, and RORγt, as well as by inducing the expression of FOXP3, IL-10, and myeloperoxidase, effectively blocking the colitis process." (PMID 39064870, 2024). "Further, CD1d+ Bregs suppressed intestinal inflammation in mice with colitis, in an IL-10-dependent manner." (PMID 39346706, 2024). "Conversely, the level of the anti-inflammatory cytokine IL-10 was decreased in the DSS-induced colitis mice colon compared with the control group, but it increased after QUE treatment." (PMID 39458282, 2024). "Another colitis model often used to investigate intestinal inflammation mechanisms is by inhibiting, knocking down, or knocking out IL‐10 in mice." (PMID 38363052, 2024). "exploit siderophores as an iron source, leading to extensive proliferation in Lcn10−/−/Il10−/− mice and inducing colitis and right-sided tumors when transferred to Il2−/− mice." (PMID 39051782, 2024). "Bifidobacterium are known to induce intestinal Th17 cells, enhance Treg mitochondrial activity, promoting IL-10 production and protecting against colitis, and are positively correlated with upregulation of γδ T cells in the colonic LP in a DSS-colitis model." (PMID 39432107, 2024). "The results demonstrated that SP decreased mRNA levels of IL-6, TNF-α, IL-17A, and IL-1β, but enhanced the mRNA level of IL-10 in mice with DSS-induced colitis." (PMID 38725846, 2024). "A mixture of Lactobacillus rhamnosus dm905 and Lactococcus lactis mitigated colitis in Il10−/− mice, partly by decreasing PXR, TGR5, VDR, CAR, the NLRP3 inflammasome, and pro-inflammatory cytokines." (PMID 39767816, 2024).
colitis (continued). "Previous studies have demonstrated that both germ-free mice and germ-free IL-10 knockout mice fail to develop colitis, thereby confirming the role of the microbiota in the initiation and progression of inflammation." (PMID 39687875, 2024). "This failure was observed only in recipients with colitis, suggesting that IL-10 acts directly on Treg cells and has an important function in the presence of inflammation." (PMID 39201260, 2024). "Previous PM inhalation studies found that urban coarse PM caused inflammatory effects, and in the context of colitis models, there are 2 existing studies on ingested PM10 effects on IL-10−/− colitis, which both reported increased inflammation." (PMID 39000289, 2024). "Adoptive transfer experiments revealed that both WT and Il10−/− Tregs significantly suppressed anti-CD40 agonistic antibody-induced colitis." (PMID 39379604, 2024). "Bifidobacterium can also protect IL-10−/− mice from developing colitis, and it is beneficial in mice with DSS-induced colitis and in the SAMP/Yit spontaneous model of Crohn’s-like ileitis." (PMID 39432107, 2024). "This change enhanced mitochondrial fitness and IL-10-mediated suppressive functions of intestinal Tregs, contributing to colitis improvement." (PMID 39687875, 2024). "IL10, which is crucial for intestinal homeostasis, offers protection from intestinal injury and limits the development of colitis." (PMID 39687875, 2024). "S. cerevisiae engineered to express and secrete interleukin-10 (IL-10) demonstrated anti-inflammatory effects in a mouse model of colitis." (PMID 39057374, 2024). "In the context of IBD, Steck and colleagues showed that E. faecalis is able to induce colitis in the mouse IL-10−/− model, in a manner that requires expression of the GelE gelatinase." (PMID 39135000, 2024). "In comparison to the MC group, TP2 significantly enhanced the expression of IL-10 (p < 0.0001)and IL-22 (p < 0.05) in the colonic tissues of colitis-induced rats." (PMID 39776580, 2024). "IL-10 is able to suppress T cell-mediated immune response and ameliorate colitis by inhibiting antigen presenting cells, and downregulate IL-1β, IL-6, and TNF-α secreted by macrophages and T cells." (PMID 38397562, 2024). "EcNP3 exhibited a restorative effect on the depletion of peritoneal anti‐inflammatory macrophages (F4/80hiCD11bhi), significantly increased the expression level of IL‐10 in macrophages, and alleviated experimental colitis." (PMID 39553425, 2024). "Independently, active inflammation is suppressed and even reversed by H. polygyrus infection in two genetic models of colitis: piroxicam treatment of Il10−/− mice and transfer of Il10−/− T cells into Rag2−/− mice." (PMID 38277692, 2024). "The concentrations of pro-inflammatory (IL6 and TGFβ) and anti-inflammatory (IL10) cytokines were determined to evaluate the immunoregulatory effects of recombinant L. strains in the context of DSS-induced colitis in mice." (PMID 38680913, 2024). "In this Resource, the authors integrate multiomics data to show the effect of the transcription factors Blimp-1 and c-Maf on IL-10 and type 1 and 17 responses, which together protect against pathobiont-induced colitis." (PMID 38609547, 2024). "S. cerevisiae strains exhibited in vivo reduction of pro-inflammatory cytokines IL-1β, IL-6 and TNF-α and promoted the expression of the anti-inflammatory cytokine IL-10 in colitis mice." (PMID 39628717, 2024). "Mechanistically, IL-10 expression by Tregs has been identified as crucial for the prevention of colitis by studies employing Foxp3CreIl10flox/flox mice." (PMID 39379604, 2024). "In previous reports, GPR68 was identified to promote intestinal inflammation in the IL10-/- murine model for colitis." (PMID 39336742, 2024). "By phase I research on Crohn's patients in humans and colitis in animal model, researchers found that L. lactis can be a good carrier for delivering IL-10." (PMID 38495751, 2024).